IL17B (interleukin 17B)
Diseases named in the same sentence as IL17B in open-access papers (continued):
Sharing a sentence is not in itself a finding about the gene and the disease.
cancer (32 papers, 2012 to 2025). A tumor composed of atypical neoplastic, often pleomorphic cells that invade other tissues. "In the forest plot, we found that IL-17B and IL-17C had important prognostic significance with hazard ratio (HR) >1 in the majority of cancers, which was recognized as a high-risk prognostic factor." (PMID 36159856, 2022). "Cancer-associated fibroblasts (CAFs) in the tumor microenvironment expressed considerably more IL-17B than fibroblasts." (PMID 34771503, 2021). "All the evidence regarding Beclin-1 ubiquitination indicates that IL-17B contributes to the regulation of the stemness of cancer cells, but the underlying molecular mechanisms are incompletely understood." (PMID 33649532, 2021). "High expression of IL-17B or its receptor has been associated with poor patient prognosis in different cancer types." (PMID 32373132, 2020). "IL-17B promotes the proliferation and survival of cancer cells in animal models, and increased IL-17B levels are linked to poor outcome in patients with several types of cancers (e.g., breast, lung, and pancreatic)." (PMID 32849528, 2020). "For instance, in mouse models, IL-17B signaling through IL-17RB promotes cancer cell survival, proliferation, and migration, while in humans, elevated IL-17B expression has been associated with poor prognosis in patients with different cancer types." (PMID 32373132, 2020). "For instance, the interleukin IL‐17B signals through IL‐17RB receptor to directly promote cancer survival, proliferation, migration, and induces resistance to therapy." (PMID 36325957, 2023). "The survival, proliferation, and migration of cancer cells are directly promoted, and resistance to conventional chemotherapy drugs is induced through the IL-17RB/IL-17B signaling pathway." (PMID 37771430, 2023). "For example, in mice, IL-17B signaling via IL-17RB facilitates cancer cell survival, invasion, proliferation, and metastasis, whereas in humans, high expression of IL-17B and IL-17RB is linked to a poorer prognostic outcome in BC sufferers." (PMID 38239641, 2023). "Although IL-17B promotes cell survival, proliferation, and migration, when measured alone, it relates to poor prognosis in patients with different types of cancer." (PMID 38068860, 2023). "IL-17B signaling directly promotes the proliferation and migration of cancer cells through IL-17RB and induces resistance to traditional chemotherapy drugs." (PMID 37686343, 2023). "Previously, we identified an IL-17RB targeting mAb which intercepts IL-17B/IL-17RB signal transduction and suppresses tumorigenesis in many types of cancer." (PMID 35214622, 2022). "Previously, we reported the findings that interleukin 17 receptor B (IL-17RB) signaling contributes to cancer survival, proliferation and metastasis upon binding to its cognate ligand IL-17B." (PMID 35214622, 2022). "While IL-17E has been shown to induce apoptosis in breast cancer cells, IL-17B as well as IL-17RB expression correlates with worse cancer outcomes." (PMID 36140808, 2022). "These functions indicate the importance of the IL-17B/IL-17RB signaling pathway for maintaining CSC homeostasis, suggesting that the IL-17B/IL-17RB signaling pathway is a new therapeutic target for cancer treatment." (PMID 33649532, 2021). "Since IL‐17RB is a common receptor for IL‐25 and IL‐17B, it is found that IL‐17B can induce pro‐neoplastic properties in cancer cells." (PMID 34128588, 2021). "A recent study indicated that in in vivo models, IL-17B conveyed directory through its IL-17RB and encouraged cancer cell survival to proliferation to relocation to resisting usual chemotherapeutic agents." (PMID 34336101, 2021). "In vivo mouse models and in vitro cell assays indicate that in different tumor cell types, IL-17B signaling is critical for tumorigenesis promoting cancer cell survival and proliferation." (PMID 32373132, 2020).
cancer (continued). "CCL5/CCR5 regulates the coupling of cancer cells and mesenchymal stromal cells, and IL-17B/17-BR stimulates chemokines or enhancing inflammation, both of them facilitate the progression and metastasis of cancer cells." (PMID 33143662, 2020). "In mouse models, IL-17B signaling through IL-17RB directly promotes cancer cell survival, proliferation, and migration, and induces resistance to conventional chemotherapeutic agents." (PMID 32373132, 2020). "The IL-17B/IL-17RB pathway is considered as a signaling cascade that promotes cancer cell survival, proliferation and migration." (PMID 32373132, 2020). "As for IL-17A, the role of IL-17B, IL-17C, IL-17D, IL-17E, and IL-17F in cancer remain controversial." (PMID 33244315, 2020). "We also underscore differences and similarities between IL-17A and IL-17B-to-F in the microbiota-immunity-cancer axis, and we highlight therapeutic strategies that directly or indirectly target IL-17 cytokines in diseases." (PMID 33244315, 2020). "IL-17B is not only involved in the immune response, but also related to development, fracture, and cancer." (PMID 28145881, 2017). "IL-17A, IL-17B, IL-17C, as well as IL-17F have been shown to promote tumor development, whereas IL-17D and IL-17E play anti-cancer roles in a context-dependent manner by activating the Nrf2 stress surveillance pathway, recruiting innate immune cells, and activating leukocytes." (PMID 36140808, 2022). "The IL-17B signaling pathway is mainly reflected in cancer diseases." (PMID 35392087, 2022). "The expression of IL-17B in pan-cancer has a significantly positive correlation with CAF, Endo, HSC, and NKT, showing that the highly expressed IL-17B may have higher immune infiltration of these cells in TME." (PMID 36159856, 2022). "However, targeting IL17B/IL17RB signaling with a newly derived anti–IL17RB antibody will block cancer cell metastasis and promote survival." (PMID 34724890, 2021). "Taking together, using IL‐17B inhibitors increases the therapeutic efficacy of rIL‐25 in cancer." (PMID 34128588, 2021). "Overall, the results elucidate the novel functions of IL-17B for CSCs and suggest that the intervention of the IL-17B/IL-17RB signaling pathway may provide new therapeutic targets for the treatment of cancer." (PMID 33649532, 2021). "A combination of rIL‐25 with IL‐17B silencing (siIL‐17B) and melatonin could vigorously inhibit cancer progression." (PMID 34128588, 2021). "Therefore, we propose that IL-17B signaling activates autophagy to regulate the stemness of cancer cells." (PMID 33649532, 2021). "Moreover, since IL‐17B and IL‐25 have a common receptor called IL‐17RB, it is also required to define which ligand is involved in the cancer progression." (PMID 34128588, 2021). "Similarly, in murine cancer models and patients, IL-17B exhibits protumor roles and IL-17E antitumor activities (see just below)." (PMID 32373132, 2020). "Following the activation of such chemokines, IL-17B promotes the recruitment of macrophages that, in turn, favors cancer cell survival and invasion as well as the recruitment of endothelial cells with vasculogenic potential, thus stimulating tumor angiogenesis." (PMID 29371916, 2017). "Wen-Hwa Lee and co-workers also clearly indicated the critical roles of IL-17B/IL-17RB signaling in cancer progression.However, it is unclear whether IL-17B exhibits potential effects on MSC in the tumor microenvironment and contributes to tumor progression." (PMID 28145881, 2017). "The IL-17 family of cytokines is composed of six members named IL-17A (commonly known as IL-17), IL-17B, IL-17C, IL-17D, IL-17E (also known as IL-25), and IL-17F with different sequence homology and functions that are important players in host defense responses, inflammation, and cancer development." (PMID 38068860, 2023). "Therefore, targeting the IL-17B/IL-17RB signaling cascade is a novel approach for cancer treatment." (PMID 33649532, 2021).
cancer (continued). "Thus, we conclude that high expression of IL-17RB in CSCs promotes cancer initiation, propagation, metastasis, and recurrence, and IL-17B and IL-17RB form a positive feedback loop that further amplifies the IL-17B/IL-17RB signaling cascade in the tumor environment." (PMID 33649532, 2021). "However, it is unclear whether the biological functions of IL-17B are elicited through its direct effects on cancer cells or CSCs." (PMID 33649532, 2021). "Therefore, targeting Il-17B or its receptor might represent an interesting therapeutic option for cancer therapy." (PMID 32373132, 2020). "Moreover, OS (p = 0.016) and DFS (p = 0.029) were significantly reduced in patients with cancers in which both IL-17B and IL-17RB were overexpressed compared with patients with cancers where only one was upregulated or where both molecules were expressed at low level." (PMID 29371916, 2017). "IL-17B/IL-17RB signaling and ERK are involved in a significant pathway that enhances the invasion and migration of cancer cells." (PMID 37686343, 2023). "Accordingly, IL-17B has been detected in neutrophils infiltrating the synovial membrane of RA patients and the stroma of CCR cancer by IHC/IF, as well as in freshly isolated neutrophils by immunoblotting, in all cases using #AF1248 Abs." (PMID 29719541, 2018). "Thus, it was suggested that IL-17E production by normal epithelium might prevent the emergence of transformed epithelial cells by inducing malignant cell apoptosis, while IL-17B produced by transformed cells promoted cancer cell survival by displacing IL-17E from its receptor." (PMID 26154409, 2015). "A signalling cascade, IL-17B/IL-17RB pathway encourages not just cancer survival but also aids in its proliferation and relocation." (PMID 34336101, 2021). "Activated IL17B/IL-17RB signaling, which increases chemokine expression via the NF-κB and ERK1/2 pathway, promotes cancer cell invasion, macrophage and endothelial cell recruitment to the primary sites, and cancer cell survival at distant organs." (PMID 33082357, 2020). "The five EV-dependent regulated genes whose expression changes were prevented by importazole (i.e. ghrelin, IL-26, IL-17B, Casp1 and CCL5) may be relevant for the pro-tumorigenic activity of cancer EVs." (PMID 28129640, 2017). "It would be interesting to test whether anti-IL-17A, IL-17B and/or IL-17E based therapies could affect tumor growth and sensitivity to chemotherapy and immunotherapy (anti-HER2) in animal models of cancer." (PMID 26154409, 2015). "Therefore, the results reveal novel functions of IL-17B for CSCs and implicate the importance of the IL-17B/IL-17RB signaling pathway in maintaining CSC homeostasis, suggesting that this pathway is a new therapeutic target for cancer." (PMID 33649532, 2021). "Therefore, targeting IL-17B rather than its receptor appears to be a better strategy for anti-cancer therapy." (PMID 32373132, 2020).
tumor (32 papers, 2010 to 2026). "The pro-tumor functions associated with the IL-17B/IL-17RB pathway are diverse and complex because they involve mechanisms that act directly on tumor cells, and also indirect mechanisms that lead to tumor microenvironment remodeling." (PMID 32373132, 2020). "IL17B has been associated with tumor progression and is increased during intestinal inflammation." (PMID 39795948, 2024). "In addition to IL-17A, numerous clinical trials have implicated the function of the IL-17B/IL-17 receptor B (IL-17RB) pathway in tumor formation and chemoresistance." (PMID 36313570, 2022). "Tumor-derived IL-17B, carried by extracellular vesicles, activates PSCs and increases the level of IL-17RB." (PMID 40536951, 2026). "IL-17RB also plays a unique role in contributing to tumor development and invasion and migration upon stimulation with IL-17B." (PMID 37686343, 2023). "The IL‐17B/IL‐17RB pathway is a signaling cascade that can either directly act on the tumor cells or indirectly leads to tumor microenvironment remodeling." (PMID 36325957, 2023). "IL-17B activates 17RB, which results in enhanced tumor cell survival, migration, proliferation, and chemoresistance in mouse models." (PMID 36313570, 2022). "The role of IL-17D towards tumor purity was the same as IL-17B, embodied in BRCA, HNSC, PAAD, SARC, TGCT, and UVM." (PMID 36159856, 2022). "Tumor-derived IL-17B carrying extracellular vesicles (EVs) activated stromal PSCs and induced the expression of IL-17RB." (PMID 34771503, 2021). "Every study point to the hindrance of the IL-17B/IL-17RB axis through downregulation of receptor expression in tumour cells, utilising diffusing anti-IL-17RB antibodies, reestablished in vitro and in vivo chemosensitivity." (PMID 34336101, 2021). "Analysis of publicly available TCGA and GTEx data showed higher IL-17B mRNA expression in the tumor than in normal tissue." (PMID 34771503, 2021). "We quantified IL-17B in human PDAC compared with the adjacent non-tumor pancreatic tissue using ELISA." (PMID 34771503, 2021). "This study also identified the alteration of TME by IL-17B signalling and subsequent tumour growth induction." (PMID 34336101, 2021). "In the present study, to investigate the effect of IL-17B/IL-17RB signaling on GC cells in vivo, we established a xenograft tumor model through subcutaneous injection of MGC-803 cells treated with rIL-17B or not into nude mice." (PMID 33649532, 2021). "We found that IL-17RB was highly expressed in GC-CSC-like cells, and that IL-17B promoted the sphere-formation ability of CSCs in vitro and enhanced tumor growth, invasion and stmness in vivo." (PMID 33649532, 2021). "We report that aberrant expression of IL-17B/RB in stromal pancreatic stellate cells (PSCs) accelerates tumor cell growth." (PMID 34771503, 2021). "Our previous study revealed that the IL-17B/IL-17RB signal promotes the growth and migration of tumor cells, and the expression of IL-17RB is positively correlated with the expression CSC markers." (PMID 33649532, 2021). "Tumor cell-derived IL-17B carrying extracellular vesicles induces the expression of the IL-17B receptor on PSCs." (PMID 34771503, 2021). "Recombinant IL-17B (rIL-17B) promoted the sphere-formation ability of CSCs in vitro and enhanced tumor growth and metastasis in vivo." (PMID 33649532, 2021). "The IL-17B/IL-17RB pathway's protumour functions are different and intricate, owing to the processes that perform unswervingly on tumours apart from unintended mechanisms which force TME reshaping." (PMID 34336101, 2021). "IL-17B signalling is crucial in aiding tumour survival and growth, many in vitro and in vivo assays identified." (PMID 34336101, 2021). "Possibly, HSCs promote liver metastasis via exosome-mediated IL-17B/IL-17RB signaling by increasing oxidative phosphorylation in metastatic tumor cells." (PMID 34771503, 2021).
tumor (continued). "The results showed that rIL-17B promoted tumor growth in a concentration-dependent manner; with an increasing concentration of IL-17B, the tumorigenicity of the cells occurred earlier, and all tumors developed earlier in the mice." (PMID 33649532, 2021). "In vivo studies showed that tumor growth and metastasis formation are reduced in mice xenografted with IL-17RB or IL-17B knockdown cells compared with parental CFPAC-1 and BxPC3 cells." (PMID 32373132, 2020). "Altogether, these studies clearly identified IL-17B and IL-17RB as key actors of cell tumorigenesis by enhancing the survival and the proliferative, migratory and invasive properties of tumor cells." (PMID 32373132, 2020). "While IL-17D and IL-17E appear to exert preponderant tumor-protective activities, IL-17B, IL-17C, and IL-17F are tumor promoting, either through a direct effect on tumor cells, or by modulating the tumor microenvironment." (PMID 33244315, 2020). "Again, elevated expression of IL-17B can promote the proliferation, migration and stemness of MSCs in circulation and tissues microenvironment, and further accelerates the tumor progression." (PMID 28145881, 2017). "In this study, we further explored the effect of IL-17B on mesenchymal stem cells in tumor microenvironment and its impact on the tumor progression." (PMID 28145881, 2017). "The results showed that IL-17B induced the expression of stemness-related genes Nanog, Sox2, and Oct4 in mesenchymal stem cells and enhanced its tumor-promoting effect." (PMID 28145881, 2017). "It has been found that activation of IL-17B/RB on tumor cells can subsequently phosphorylate and activate ERK1/2, enhance the production of a series of chemokines, such as C-C motif chemokine ligands, and ultimately promote the recruitment of neutrophils, lymphocytes, and endothelial cells." (PMID 39906741, 2024). "Both CCR3 and IL17B have been found to be related to the role of tumor microenvironment in regulating tumor growth and metastasis, and may be new immunotherapy targets." (PMID 37316840, 2023). "Moreover, IL-17B signaling can significantly modify the tumor microenvironment by increasing cytokine and chemokine secretion, leading to enhanced tumor progression." (PMID 36313570, 2022). "For example, the expression of IL-17B was strongly negatively associated with DNAss and RNAss in PCPG, suggesting that high expression of IL-17B may lead to low stemness of tumor in PCPG." (PMID 36159856, 2022). "We hypothesize that a tumor-promoting interaction of PSCs and tumor cells via IL-17B/IL-17RB may affect energy metabolism." (PMID 34771503, 2021). "Thus, the in vivo results thus further corroborate that IL-17B/IL-17RB signaling strengthens the peritoneal tumorigenesis and invasive abilities of tumor cells." (PMID 33649532, 2021). "Tumor cell-derived extracellular vesicles transport IL-17B into the cytosol of PSCs." (PMID 34771503, 2021). "Here we show a hitherto unknown metabolic cooperation between pancreatic stellate cells (PSCs) and tumor cells through Interleukin 17B/Interleukin 17B receptor (IL-17B/IL-17RB) signaling." (PMID 34771503, 2021). "Our results suggest a pro-tumorigenic effect of stroma-to-tumor IL-17B/IL-17RB signaling and that specific inhibition of the IL-17B receptor could be an effective therapy to suppress the metabolic tumor-stroma cooperation." (PMID 34771503, 2021). "The research has implied a crucial role of the IL-17B/IL-17RB signaling cascade in tumor biology." (PMID 33649532, 2021). "However, we identified tumor cell derived extracellular vesicles (EVs) as inducers of increased IL-17RB expression in PSCs that carry IL-17B." (PMID 34771503, 2021). "Here, we investigate the IL-17B/RB-mediated interactions between the tumor and the stroma." (PMID 34771503, 2021). "If IL-17B mediates the crosstalk between PSCs and tumor cells, the question is whether IL-17B promotes tumor growth." (PMID 34771503, 2021).